ATRX (ATRX chromatin remodeler)
Diseases named in the same sentence as ATRX in open-access papers (continued):
Sharing a sentence is not in itself a finding about the gene and the disease.
glioma (continued). "Having implicated the immune microenvironment as a potential causative factor promoting indolence in ATRX-deficient glioma, we sought to determine the extent to which ATRX depletion promotes increased immune cell infiltration in our in vivo models." (PMID 38272925, 2024). "Genes with synergistic relationship with IDH1 mutations in glioma such as ATRX have been previously reported, representing a glioma subgroup distinct from those with co-mutations of IDH1 with CIC and FUBP1 mutations." (PMID 39160568, 2024). "Previous studies have primarily focused on gliomas with ATRX inactivating mutations that leading to resistance to chemotherapeutic agents." (PMID 38898533, 2024). "ATRX knockout in preclinical glioma models was associated with sensitivity to DNA damaging agents, including PARP and ATR inhibitors." (PMID 38473300, 2024). "Our results and the fact that ATRX mutations exist in a majority of gliomas, certainly make ATRX an interesting molecule for future study with CBL0137 administration." (PMID 39315270, 2024). "Inactivation of the SWI/SNF chromatin remodeler gene, α-thalassemia retardation X-linked (ATRX), represents a common glioma-associated molecular alteration with the potential to substantially impact the tumor microenvironment." (PMID 38272925, 2024). "None of the CN patients examined in the present study presented any mutations in the TERT promoter or ATRX region, which are frequently observed in glioma." (PMID 38609519, 2024). "Up to 25% of gliomas exhibit ATRX mutations, with specific percentages including 67% of WHO grade II astrocytomas, 73% of WHO grade III astrocytomas, and 57% of secondary glioblastomas." (PMID 39479502, 2024). "To investigate the role of ATRX deficiency in regulating inflammation in gliomas, we developed both mouse and human experimental systems using glioma cell lines that exhibit intact innate immune signaling pathways." (PMID 38272925, 2024). "As a therapeutic drug for glioma, TMZ inhibits tumor cell proliferation mainly by inhibiting DNA damage repair in ATRX mutation-positive glioma." (PMID 39479502, 2024). "The ATRX mutation has been found in several cancers, including glioma, osteosarcoma and pancreatic neuroendocrine tumors." (PMID 37570630, 2023). "Mutations in ATRX are predominantly loss of function and are enriched in specific cancer types, including low-grade gliomas, soft tissue sarcomas, pancreatic neuroendocrine tumors, and uterine corpus endometrial carcinomas." (PMID 37200088, 2023). "ATRX mutation in glioma disturbed the cell-cycle phase transition, downregulated the expression of Checkpoint Kinase 1 (CHEK1) and even inhibited radio-sensitization." (PMID 37570630, 2023). "ATRX has been observed to be frequently mutated (typically in at least 80% of patients in case series but up to 100% in some) in H3.3-G34R/V mutant gliomas." (PMID 37509641, 2023). "In glioma, histone and ATRX mutations have been associated with genetic instability, which results from abnormal histone mark deposition in these cells." (PMID 36647827, 2023). "Abnormal telomere maintenance seems to be a central process in gliomagenesis, which is implied by the mutual exclusivity of TERT promoter and ATRX mutations in IDH-mutant adult gliomas." (PMID 36765553, 2023).
glioma (continued). "Specific point mutations in H3.3 (K27M/G34R) and its ATRX chaperone are frequent events in pediatric gliomas." (PMID 38066546, 2023). "In pediatric gliomas, mutations in H3.3 genes are also observed in addition to ATRX mutations, with strong correlation to the ALT phenotype." (PMID 37107548, 2023). "The SRH and genetic encoders were integrated to predict IDH, 1p19q, and ATRX mutations and thereby achieve molecular classification of gliomas by WHO criteria." (PMID 38161802, 2023). "ATRX mutation is associated with improved OS in gliomas and worse OS in pancreatic neuroendocrine tumors." (PMID 37200088, 2023). "Comprehensive genomic profiling of 12 ATRX-deficient and 13 ATRX-intact IDH-wildtype adult high-grade gliomas revealed that ATRX and pTERT mutations are mutually exclusive." (PMID 37891325, 2023). "In terms of well-known molecular markers, IDH mutation, 1p/19q codeletion, MGMT promotor methylation, wild-type TERT promoter, and ATRX mutation glioma samples correlated with lower infiltration of reactive astrocytes." (PMID 37416308, 2023). "ATRX, a chromatin remodeling protein, is considered to be associated with the prognosis of patients with glioma and a novel therapy target." (PMID 35668574, 2023). "DAXX forms a complex with the ATRX (α-thalassaemia with mental retardation, X-linked) chromatin remodeller, and this complex is also frequently mutated in gliomas, strongly suggesting that the ATRX/DAXX/H3.3 axis is pivotal in these cancers." (PMID 38066546, 2023). "Point mutations in histone variant H3.3 (H3.3K27M, H3.3G34R) and the H3.3-specific ATRX/DAXX chaperone complex are frequent events in pediatric gliomas." (PMID 38066546, 2023). "Another report showed that ATRX binds to the promotor region of rDNA and they observed increased ribosome biogenesis in gliomas with nonsense mutations, which is in line with our generated ATRX KO models." (PMID 37540673, 2023). "TERT promoter mutations and loss of function ATRX mutations are usually mutually exclusive, as has been observed in gliomas." (PMID 37629169, 2023). "We demonstrate that four multi-targeted receptor tyrosine kinase inhibitors (RTKi) and a specific inhibitor targeting the platelet-derived growth factor receptor (PDGFRi) exhibit higher toxicity in ATRX-deficient high-grade glioma cells." (PMID 35406561, 2022). "NF1-associated gliomas in the molecular high-grade group often had increased cellular density, higher Ki-67 labeling indices, and loss of p16 and/or ATRX expression on immunohistochemical evaluation compared to the molecular low-grade group." (PMID 35945463, 2022). "In glioma, mostly all mutations in ATRX are inactivating, resulting in the loss of protein expression." (PMID 35382567, 2022). "ATRX mutations occur in a variety of human cancers such as hepatocellular carcinoma, pancreatic neuroendocrine tumors, and gliomas." (PMID 35406561, 2022). "Among them, ATRX was frequently mutated in low‐grade gliomas (39%), uterine corpus endometrial carcinoma (UCEC, 18%), and glioblastoma multiforme (10%)." (PMID 35789070, 2022).
glioma (continued). "Our longitudinal data from glioma samples demonstrated that the switching of TMM groups or changes in telomerase activity are common scenarios in glioma progression, although the mutational status of TERTp and ATRX loss are mostly unchanged." (PMID 35953846, 2022). "A somatic ATRX (c.6406G>A, p.Asp2136Asn) missense variant was identified and has been reported in glioma (astrocytoma grade IV) and endometrioid carcinoma." (PMID 35323929, 2022). "Sunitinib treatment significantly reduced clonogenic survival of U-251 ATRX KO cells compared to WT cells,further validating the toxicity of RTKi for ATRX-deficient high-grade glioma cells." (PMID 35406561, 2022). "ATRX mutations are also frequent in patients with low-grade gliomas, and they are predictive of a favorable prognosis." (PMID 36292695, 2022). "In this study, we aimed to identify drugs that exhibit synthetic lethality with ATRX loss and, thus, exploit ATRX deficiency for the treatment of high-grade glioma patients harboring ATRX mutations." (PMID 35406561, 2022). "Conversely, (inactivating) mutations for ATRX lead to a reduction of ATRX in glioma cell nuclei, which means that gene regulation via chromatin remodeling is no longer regulated, thereby promoting stabilization of the glioma cell." (PMID 34687436, 2022). "This is well established in ALT‐positive gliomas in which the IDH1R132H mutation is associated with ATRX loss." (PMID 35920001, 2022). "We demonstrated that the TMM status in gliomas cannot be simply defined and cannot be predicted by tumor histology or by the presence of gene mutations such as TERTp or ATRX loss." (PMID 35953846, 2022). "All ATRX KO high-grade glioma cell lines used in this study were more sensitive to RTKi and PDGFRi than ATRX WT cells, independently of the type of mutation in ATRX." (PMID 35406561, 2022). "It is widely believed that ALT in cancers is tightly connected with inactivating mutations in the ATRX gene as shown by previous studies and that the presence of TERTp mutation and ATRX mutation are mutually exclusive in gliomas." (PMID 35953846, 2022). "These phenomena are coincident with the consensus that mutations in IDH1 and ATRX are the initiating events for the development of many gliomas, and their presence dictates favourable clinical behaviour." (PMID 35194922, 2022). "The loss of nuclear ATRX chromatin remodeler (ATRX) in an IDH-mutant glioma is now sufficient for the diagnosis of an astrocytic lineage tumor without the need for 1p/19q codeletion analysis." (PMID 36249063, 2022). "A recent study has shown the role of ATRX as an epigenetic regulator in glioma development, whereas the effects of ATRX mutations in ALTs, a non-telomerase-dependent telomere lengthening mechanism, are well established." (PMID 35382567, 2022). "We have identified that ATRX-deficient glioma cells are sensitive to several multi-targeted receptor tyrosine kinase and specific platelet-derived growth factor receptor inhibitors, some of which are currently under study in clinical trials." (PMID 35406561, 2022). "Despite RTA changes and TMM switching with glioma progression, the mutational status of TERTp and ATRX loss remained unchanged in most cases, except in 4 cases of GBM." (PMID 35953846, 2022). "In this study, we have demonstrated that ATRX deficient cells, including patient-derived high-grade glioma cell lines, are particularly sensitive to RTKi (pazopanib, nintedanib, sunitinib, sorafenib) and to a specific PDGFRi (CP-673451)." (PMID 35406561, 2022). "Recently, an ATRX-deficient genetically engineered glioma model demonstrated that loss of ATRX reduces median survival and increases genetic instability." (PMID 36226186, 2022). "ATRX is rarely mutated in adults with primary high-grade gliomas, but is more frequent in younger adults with lower-grade gliomas." (PMID 35991838, 2022).
glioma (continued). "We have conducted a drug screen searching for compounds toxic to ATRX-deficient cells, a frequent scenario in cancer, and particularly in high-grade gliomas." (PMID 35406561, 2022). "Most ATRX mutations found in glioma patients are truncating mutations leading to the complete loss of the functional ATRX protein." (PMID 35406561, 2022). "In our report, ATRX mutation was identified in Case #1 who was a young adult with lower-grade gliomas." (PMID 35991838, 2022). "The authors also report better survival time in a xenograft and a syngeneic murine glioma model (ATRX KO cell line) and suspect an interaction between ATRX mutation and immune signaling in glioma cells." (PMID 34687436, 2022). "The ATRX mutation was principally found in NT-4 (133/224 samples, 59.4%) and NT-1 glioma clusters (46/168 samples, 27.4%), as expected." (PMID 35455749, 2022). "reports a BRD3/4-dependent induction of an immunosuppressive transcriptome, marked by upregulation of PD-L1/2, IL-33, CXCL8/9, CSF2, and IL-6, in ATRX-deficient glioma cells." (PMID 36212415, 2022). "While most ATRX mutations in gliomas are loss of function due to truncations, missense mutations also occur with increased incidence in the helicase domain compared to other regions of the protein." (PMID 35998910, 2022). "We confirmed that TMM status does not always correlate with signatures such as TERTp mutation or ATRX loss in gliomas." (PMID 35953846, 2022). "We also confirmed known associations between age and mutations in tumour suppressors IDH1- and ATRX- in both high grade glioblastoma and lower grade gliomas, IHD1- and ATRX- were more frequent in tumours derived of younger individuals." (PMID 35017538, 2022). "1p/19q codeletion is mutually exclusive with ATRX mutation, which characterizes glial tumors of astrocytic lineage." (PMID 34020723, 2021). "ATRX deletion mutations occur in various malignancies, including glial tumors, pediatric adrenocortical carcinoma, osteosarcoma, and neuroblastoma." (PMID 34422662, 2021). "Consistent with this, point mutation of Isocitrate Dehydrogenase 1 (IDH1) (R132H), which is frequently found to be coincident with ATRX mutations in certain cancers, including glioma, is sufficient to create tumorigenic cells with ALT characteristics." (PMID 34828344, 2021). "The mutated ATRX gene is frequently detected in several tumors, including adrenocortical carcinoma, gliomas, GBM, neuroblastoma, and osteosarcoma, and pancreatic neuroendocrine tumors(panNETs), which are a group of endocrine tumors arising in the pancreas." (PMID 34947936, 2021). "In IDH-mutant gliomas, ATRX loss indicates astrocytic phenotype, while ATRX retention and H3K27me3 loss identify oligodendroglial phenotype." (PMID 34165590, 2021). "Recent studies support our conclusion that a global loss of CTCF binding explains the global increase in open chromatin observed in ATRX-deficient human and murine gliomas and point to a mechanism by which these differences regulate gene expression." (PMID 34763709, 2021). "In combination with IDH mutations, ATRX mutation status is one of the critical defining markers used for molecular classification of gliomas." (PMID 34277415, 2021). "ATRX-deficient glioma cells accumulate replication problems and DNA damage due to the lack of the helicase ATRX." (PMID 33632214, 2021). "They found that these combined modalities were able to differentiate glioma grade (AUC 0.852), ATRX mutation (AUC 0.851), MGMT mutation (AUC 0.757), IDH1 mutation (AUC 0.887), and 1p19q codeletion (AUC 0.978)." (PMID 34194287, 2021).
glioma (continued). "Lastly, ATRX loss and hTERT mutations rarely occur together in gliomas, and hTERT alterations are much more prevalent in the oligodendrocytic lineage." (PMID 34069193, 2021). "We conclude that ATRX loss-of-function in IDH-mutant glioma orchestrates chromatin and gene-expression differences that regulate glial identity and myeloid-cell induction." (PMID 34763709, 2021). "In IDH-wild type gliomas, the presence of ATRX mutations served as a favorable marker of longer patient survival." (PMID 33678158, 2021). "ATRX mutations are also found in different cancers, including glioma, neuroblastoma, pancreatic neuroendocrine tumors, and childhood osteosarcoma." (PMID 32533344, 2020). "Crucial molecular markers such as mutations in IDH, ATRX and 1p/19q codeletion status are now central in the pathological diagnosis of glioma." (PMID 32047544, 2020). "The tumor types with the highest prevalence of ATRX/DAXXtrunc mutations were liposarcomas (32%), adult lower grade gliomas (28%), pancreatic endocrine tumors (23%), and osteosarcoma (17%), all of which have previously been associated with ALT12,31." (PMID 32024817, 2020). "The nature of the interaction between H3.3 and ATRX/DAXX mutations in driving pediatric gliomas remains to be elucidated." (PMID 33348922, 2020). "WEE1 inhibitor can selectively inhibit the proliferation of glioma and hepatocellular carcinoma cells with ATRX mutations, which indicates that the synthetic lethal interaction between ATRX and WEE1 can be applied in an extensive range of tumors." (PMID 32883316, 2020). "ATRX is a clinically relevant marker of lower-grade gliomas and has been associated with increased telomere length." (PMID 32604718, 2020). "One study on the prediction of ATRX mutation in low-grade gliomas represented brilliant results with AUC of 0.925 in the validation group." (PMID 32547944, 2020). "AZD1775 also selectively inhibited the proliferation of patient-derived primary cell lines from gliomas with naturally occurring ATRX mutations." (PMID 32984050, 2020). "TERT promoter mutations and ATRX alterations have been described across glioma subtypes in a mutually exclusive pattern." (PMID 33747896, 2020). "Nevertheless, our findings indicate that the targeted approach of G4 stabilization has considerable therapeutic potential in the treatment of ATRX-deficient glioma, along with other ATRX-mutant cancers." (PMID 30808951, 2019). "To this point, we recently demonstrated that ATRX deficiency induces extensive chromatin remodeling and transcriptional shifts in putative glioma cells of origin, driving disease-relevant phenotypes that modulate both cellular motility and differentiation." (PMID 30808951, 2019). "We found that G4 stabilization with multiple distinct agents selectively targeted ATRX-deficient glioma cell lines and tumors, both in vitro and in vivo." (PMID 30808951, 2019). "Current practice is to utilize Clinical Laboratory Improvements Amendments (CLIA)-approved and commercially available monoclonal antibodies (mAbs) for the most common mutation of IDH1 and ATRX for routine grading of gliomas." (PMID 31091655, 2019). "Here we report that ATRX loss in isogenic glioma model systems induces replication stress and DNA damage by way of G-quadruplex (G4) DNA secondary structure." (PMID 30808951, 2019).